GTF3C2-AS2 (GTF3C2 antisense RNA 2)
Synonyms: AC074117.10; AC074117.1
Gene: Long non-coding RNA gene on chromosome 2 (27,356,246 to 27,367,881, forward strand). Ensembl gene ENSG00000234072.
Diseases named in the same sentence as GTF3C2-AS2 in open-access papers:
GTF3C2-AS2 is named in the same sentence as 1 disease in open-access papers, as found by Europe PMC text mining. Sharing a sentence is not in itself a finding about the gene and the disease.
GTF3C2-AS2 shares sentences with these, for which no sentence is quoted: cancer (1 paper).